CRP (C-reactive protein)
Diseases named in the same sentence as CRP in open-access papers (continued):
Sharing a sentence is not in itself a finding about the gene and the disease.
psychosis (continued). "Within this context, the CRP plasma levels may indicate nonresolving inflammation, activation of microglia, and subsequent downstream effects on brain structure and function via disordered synaptic pruning affecting crucial neurodevelopmental stages, ultimately leading to psychosis." (PMID 35151465, 2022). "As hypothesized, meta-analyses found elevations of biomarkers often considered “proinflammatory,” specifically neutrophil/lymphocyte ratio, TNF, CRP, IL-6, and total WBC, in youth with threshold psychosis compared to youth without psychosis." (PMID 38141839, 2024). "Mouse models revealed that CRP has no virtual effect on BBB permeability in smaller amounts but impairs its function and increases paracellular permeability in higher amounts that may be achieved during high systemic inflammation or pro-inflammatory states like psychosis." (PMID 34884840, 2021).
type 1 diabetes (75 papers, 2012 to 2025). "High-sensitivity C-reactive protein (hs-CRP) is a widely used clinical biomarker of systemic inflammation, implicated in many chronic conditions, including type 1 diabetes (T1D)." (PMID 38999806, 2024). "The haemoglobin A1c significantly correlated with hs-CRP levels and cardiovascular risk prediction in type 1 diabetes mellitus (T1DM) and T2DM." (PMID 34356982, 2021). "Higher GA levels were noted to be associated with older age, type 1 diabetes, insulin use, 2.5% glucose dialysate, and higher CRP levels." (PMID 30824808, 2019). "Higher HbA1c levels were noted to be associated with higher rates of type 1 diabetes and insulin use, 2.5% glucose dialysate, a lower proportion of males, and higher hemoglobin and CRP levels." (PMID 30824808, 2019). "A positive association of CRP levels with BMI at diagnosis of type 1 diabetes was already noted in a previous study." (PMID 22448235, 2012). "Also, considering the role of CRP as a prognostic marker, we sought to demonstrate the association of this biomarker with exercise in patients with type 1 diabetes." (PMID 35178206, 2022). "As inflammation is considered the key modulator for diabetic pathogenesis and its complications in hearts and kidneys, several studies connected the elevation in CRP levels with the incidence of Type I diabetes." (PMID 36984840, 2023). "The present study investigated the effect of aerobic and resistance training on blood CRP level of type 1 diabetic patients as a protective marker on cardiovascular cells." (PMID 35178206, 2022). "In summary, this study shows that serum Mg2+ levels are negatively associated with glycaemic control and to inflammation (log10 hs-CRP), but this relationship is limited to people with type 1 diabetes who are probably insulin resistant." (PMID 35440685, 2022). "In patients with type 1 diabetes both fasting LPS and LPS-AUC correlated with CRP (fasting r = 0.428; p = 0.009, AUC r = 0.338; p = 0.044) and insulin dose (fasting r = 0.479; p = 0.004, AUC r = 0.528; p = 0.001)." (PMID 24959195, 2014). "Youth with type 1 diabetes and public insurance had higher hemoglobin A1c (HbA1c), body mass index, hs-CRP, and blood pressure (p < 0.05) than those with private insurance." (PMID 24955334, 2014). "Patients with type 1 diabetes had significantly higher levels of HbA1c, as well as CRP in comparison to the age and sex-matched healthy individuals from the control group." (PMID 24677179, 2014). "The goal of this study was to investigate the influence of sucrose intake on anthropometric variables, body composition, lipemia, glycemic control and CRP levels in subjects with type 1 diabetes." (PMID 24499591, 2013). "This was the first clinical trial to assess the influence of sucrose in these variables in individuals with type 1 diabetes and showed a link between sucrose intake and increase of CRP." (PMID 24499591, 2013). "When examining PS exposure, we again observed hyposensitivity to PGI2 inhibition in the type 1 diabetes group compared with control participants when platelets were stimulated with CRP-XL or a combination of SFLLRN/CRP-XL, which was only observed with the higher concentration of the inhibitor." (PMID 40304758, 2025). "Additionally, women with type 1 diabetes exhibited significantly higher (p = 0.008) CRP compared with healthy controls." (PMID 37679748, 2023). "A previous study has suggested that CRP levels are elevated in type 1 diabetes." (PMID 35178206, 2022). "Endothelial dysfunction is manifested by increased expression of adhesion molecules, e.g. C-reactive protein as well as, soluble vascular cell adhesion molecule-1 (sVCAM-1), intracellular adhesion molecule-1 (sICAM-1), and E-selectin, as was shown in type 1 diabetes (T1D) patients." (PMID 34603200, 2021). "Our data show a rise in MPO levels and a correlation with hs-CRP levels, prompting the hypothesis that this enzyme is also important in the development of microvascular alterations in type 1 diabetes." (PMID 32650465, 2020).
type 1 diabetes (continued). "However, besides sex and BMI, the risk factors related to MetS in the type 1 diabetes were different as follows: age, LDL-C, and CRP." (PMID 31049079, 2019). "In spite of C-reactive protein (CRP) levels in patients with recent-onset type 1 diabetes being the same as those measured in the control group, elevated CRP levels have been observed in long-term type 1 diabetes patients." (PMID 26881236, 2016). "However, the results of our analysis lead us to conclude that patients with type 1 diabetes have enhanced inflammatory response, which is manifested by increased values of CRP, HbA1c, IL-12, and IL-18." (PMID 24677179, 2014). "Therefore, further clinical studies are needed to assess the relationship between sugars and CRP levels in subjects with type 1 diabetes." (PMID 24499591, 2013). "In humans, serum levels of proinflammatory cytokines and C-reactive protein (CRP) are elevated in newly-diagnosed type 1 diabetes patients compared to age-matched controls, and increased TLR expression or responsiveness of PBMCs from these patients is associated with elevated NF-κB signaling." (PMID 24147110, 2013). "However, this study demonstrates, for the first time, that the estrogen-mediated improvement in vascular endothelial function is lost in the presence of type 1 diabetes, a finding that persists after controlling for baseline differences in systemic inflammation (i.e., CRP) and BMI between groups." (PMID 37679748, 2023). "However, the DCCT study did not observe the association between hs-CRP and changes of albuminuria in patients with type 1 diabetes after 9 years of follow-up." (PMID 32587865, 2020). "The lack of support for a causal link between CRP and BP, and the observation that both derive from a common antecedent (BMI), suggests that weight gain should be monitored during treatment of individuals with type 1 diabetes." (PMID 29101422, 2018). "Thirdly, although we found association of CRP variant with DR in Chinese patients with T2DM, whether this effect is restricted to T2DM is still unknown and needs to be investigated in studies among patients with type 1 diabetes and other ethnic groups." (PMID 25887518, 2015). "In conclusion, a higher than median level of plasma CRP at baseline is associated with better preservation of beta cell function in newly diagnosed patients with type 1 diabetes treated with atorvastatin while such an association is not seen in patients in the placebo group." (PMID 22448235, 2012). "Obese children with new onset type 1 diabetes are more likely to have higher pro-inflammatory markers (leptin, visfatin, chemerin, TNF-α, CRP) and lower anti-inflammatory markers (adiponectin, omentin) compared to non-obese peers with type 1 diabetes." (PMID 33828529, 2021). "In people with type 1 diabetes and decreased HRV parameters, intervention for four weeks with beta-blocker (atenolol) not only increased HRV measures but also decreased the levels of the inflammatory marker C-reactive protein." (PMID 32908447, 2020). "This is consistent with our previous finding showing that ANXA1 levels did not correlate with CRP in patients with type-1 diabetes." (PMID 30972066, 2019). "Further, when comparing stages CRP and IRP, seven KOs were significantly down-regulated or up-regulated, including Alanine, aspartate and glutamate metabolism, beta-Alanine metabolism, and Type I diabetes mellitus." (PMID 28209181, 2017). "In patients with type 1 diabetes ApN was best predicted by CrCl, BMI, WBC, CRP, and age." (PMID 26089882, 2015). "Patients with type 1 diabetes mellitus (T1DM) showed significantly higher serum levels of CML and high-sensitivity C-reactive protein (CRP) than the control group via an increase in Toll-like receptor 4 (TLR-4) expression in monocytes." (PMID 36077532, 2022).
type 1 diabetes (continued). "However, there have been no studies yet that linked inflammatory biomarkers CRP, IL-6, IL-10, TNF-α, and NF-κB in saliva from adult individuals with type 1 diabetes with and without microvascular complications." (PMID 35788667, 2022). "In 543 patients divided into two groups based on the presence or absence of any complication of type 1 diabetes, circulating levels of C-reactive protein, interleukin-6, and tumor necrosis factor-α were increased in individuals with complications compared with those without." (PMID 29910771, 2018). "In addition, increases in CRP, but not in CAMs, have been shown to depend on the degree of weight gain in insulin-treated patients with type 1 diabetes." (PMID 29101422, 2018). "The inflammatory markers CRP, sCD14 and SAA varied only modestly during the day and the patients with type 1 diabetes were no different from the controls." (PMID 24959195, 2014).
Autoimmunity (74 papers, 2004 to 2026). The occurrence of an immune reaction against the organism's own cells or tissues. "Baseline ACE and ACE2 may be associated with disease duration, markers of inflammation (CRP), autoimmunity (RF) and vascular pathophysiology (FMD, IMT)." (PMID 35155468, 2021). "While both elevated and insufficient levels of CRP have been linked with disease progression in a variety of autoimmune disorders, the increased levels of CRP observed after MI in humans is believed to promote complement activation in the infarct leading to increased cardiomyocyte death." (PMID 29163503, 2017). "These mouse model results suggest CRP has a tonic, baseline suppressive effect on inflammation that helps prevent autoimmunity." (PMID 40943152, 2025). "C-reactive protein (CRP), a marker of inflammation and autoimmunity, was also elevated in the sera of homozygous mutant mice." (PMID 41279060, 2025). "Clinically, chronic inflammation manifests along a spectrum of conditions from low-grade ‘inflammaging’ that can be measured by blood C-reactive protein (CRP) and cytokines, to tissue-destructive autoimmunity and fibrosis." (PMID 41440484, 2025). "In one of the cases, the patient had only this altered result, while the other patient had other findings, such as reactive ANA and high CRP, suggestive of autoimmunity." (PMID 41259457, 2025). "In the final cohort of 136,691 patients (median age of 55.4 years, 62% female), the AUC for autoimmune conditions was 0.71 (95% CI 0.60–0.72) for the CRP and 0.71 (95% CI 0.69–0.72) for the ESR." (PMID 38285324, 2024). "When used as a surrogate biomarker in certain autoimmune conditions, CRP has been found to be less specific and useful than other biomarkers." (PMID 37476185, 2023). "CRP functions as an important modulator of host defense against bacterial infection, tissue injury and autoimmunity." (PMID 37564640, 2023). "In laboratory medicine, inflammation due to infections, allergy, cancer, or autoimmunity is routinely assessed by a differential white blood cell count, by erythrocyte sedimentation rate or by C-reactive protein (CRP) levels in peripheral blood." (PMID 35041075, 2022). "High levels of CRP have been related to the presence of a systemic inflammatory process of autoimmunity in CU and, therefore, to disease activity." (PMID 33292453, 2020). "With CRP ≥100 mg/L (n = 1552), 501 (32.3%) developed one or more relevant diseases: 113 (7.2%) cancers, 99 (6.4%) autoimmune conditions, and 317 (20.4%) infections." (PMID 31208976, 2019). "Well-known markers of inflammation and autoimmunity, such as C-reactive protein (CRP), erythrocyte sedimentation rate (ESR), rheumatic antibodies (ANA, dsDNA, ENA, ANCA), and oligoclonal bands do not play a decisive role in PACNS." (PMID 31244756, 2019). "Tests included complete blood cell count, routine blood chemistry testing, complement components 3 and 4, C-reactive protein, and a panel of serological analyses for autoimmunity." (PMID 28701998, 2017). "This scenario is consistent with the protective effect of hepatically derived/blood-borne human CRP that we have documented in other mouse models of autoimmunity." (PMID 26421184, 2015). "In this article we review and update the evidencegenerated in CRPtg by our group and in vitro by others' that indicates CRP is morethan just an antimicrobial molecule and convenient marker of inflammation - rather,it protects against autoimmunity." (PMID 15559367, 2004). "Chronic alterations or dysregulation in C4, PEDF, CRP, and SAP may predispose individuals to inflammation and tissue damage, leading to the development of self-antigens and autoimmunity." (PMID 40362185, 2025). "As a consequence of the relationships observed between CRP, SAP, PEDF, and C4, and their known associations with stress and autoimmune conditions, these results may help define patterns of inflammation involved in the stress-induced autoimmune process." (PMID 40362185, 2025).
Autoimmunity (continued). "It is also possible that CRP protects against autoimmunity in general, as has been hypothesized previously, by altering the levels of inflammatory cytokines in vivo." (PMID 38650931, 2024). "Also, potential CRP homology with other human proteins should be studied to prevent potential immunoglobulin cross-reactions and further autoimmunity." (PMID 37873776, 2023). "The contributory role of CRP in the development of autoimmunity is widely debated owing to reports of diminished numbers of pathogenic autoantibodies seen in those with prolonged low-dose exposure to CRP25; however, this remains speculative." (PMID 39554800, 2023). "Therefore, CRP plays a crucial role in the innate immune system of the host and in the defense against autoimmunity." (PMID 38004039, 2023). "Additional CRP ligands have been identified in recent years including nuclear antigens such as histones and chromatin as well as proteins from small nuclear RNP particles, fibronectin, laminin and polycations, which points to an important regulatory role of CRP in the development of autoimmunity." (PMID 32246830, 2020). "Evidence for autoimmunity (positive anti-thyroid peroxidase antibodies, anti-nuclear antibodies or autologous serum test) was found in 45.2% (n = 19/42), and high C-reactive protein was present in 14.3% (n = 6/42), half of these also had positive antinuclear antibodies." (PMID 33292453, 2020). "The predictive factors of age, presence of DU, lung fibrosis, CRP elevation and muscle weakness represent important aspects of the disease and also correspond to the key characteristic features of vasculopathy (DU), autoimmunity/inflammation (CRP elevation) and tissue fibrosis (lung fibrosis)." (PMID 31227488, 2019). "CRP is released by hepatocytes in response to pro-inflammatory cytokines and functions to activate the classical complement pathway which in turn prevent autoimmunity and defend against infection." (PMID 30858869, 2019). "Given that human CRP can utilize human FcγRIIB expressed by CD11c+ cells in transgenic mice, it is possible that the same or a similar CRP→FcγRIIB pathway operates in humans to regulate tolerance and prevent autoimmunity." (PMID 29556231, 2018). "Since a chronic inflammatory state persists in elderly people because of the appearance of autoimmunity and chronic inflammation of the upper respiratory and urinary tracts, and so on, the levels of inflammatory markers, such as CRP, IL6, and TNFα are likely to be elevated." (PMID 22485129, 2012). "It is possible that leptin, CRP, or IL-6 levels may be confounded by ethnic differences in inflammatory or autoimmune conditions; however, this is unlikely given that the women in this study were apparently healthy and relatively young." (PMID 21331287, 2011). "The ability of CRP to bind nuclear antigens, as well as its ability to increase the clearance of host apoptotic and necrotic cells, has led to the theory that CRP may prevent autoimmunity." (PMID 19436291, 2009). "In addition, CRP appears to play a very important role in preventing autoimmunity by targeting apoptotic and necrotic cells for removal." (PMID 19690638, 2007). "Human C-reactive protein is a cyclic oligomer, which binds to phosphocholine in a Ca2+-dependent manner and plays an important role in protection against infection, clearance of damaged tissue, prevention of autoimmunity as well as in regulation of the inflammatory response." (PMID 40398506, 2025). "Moreover, in CSU patients, we analyzed markers of inflammation (ESR, DD, CRP), atopy (prick test, IgE quantification), and autoimmunity (anti-thyroid antibodies and indirect basophil activation test).To evaluate the clinical activity, the Urticaria Activity Score 7 (UAS 7) test was used." (PMID 39229257, 2024).